NSG2 (neuronal vesicle trafficking associated 2)
Synonyms: Hmp19; CALY3
Tractability: Antibody: UniProt places it where antibodies can reach, with medium confidence; UniProt predicts a signal peptide or a membrane-spanning region. PROTAC: its protein half-life has been measured.
Gene: Protein-coding gene on chromosome 5 (174,045,706 to 174,243,501, forward strand). Ensembl gene ENSG00000170091.
Subcellular location: Membrane; Golgi apparatus, trans-Golgi network membrane; Cell projection, dendrite; Endosome membrane; Early endosome membrane; Late endosome membrane; Lysosome lumen; Cytoplasmic vesicle membrane; Golgi apparatus, Golgi stack membrane; Endosome, multivesicular body membrane
Subcellular location (Human Protein Atlas): Golgi apparatus
Gene Ontology:
Molecular function: protein binding; clathrin light chain binding
Biological process: clathrin coat assembly; endosomal transport; regulation of postsynaptic membrane neurotransmitter receptor levels
Cellular component: Golgi apparatus; cytoplasmic vesicle membrane; dendrite; early endosome; early endosome membrane; endosome; endosome membrane; Golgi cis cisterna membrane; late endosome; late endosome membrane; lysosomal lumen; membrane; multivesicular body membrane; trans-Golgi network membrane; glutamatergic synapse; Golgi cisterna membrane; postsynaptic density membrane
Genetic constraint (gnomAD): Loss-of-function variants: 1 observed, 9.88 expected, observed/expected ratio (o/e) 0.1, 90% interval 0.035 to 0.48. That is too few expected variants to judge how well the gene tolerates losing a copy. Missense variants: 135 observed, 179.41 expected, observed/expected ratio (o/e) 0.75, 90% interval 0.65 to 0.87. Synonymous variants: 80 observed, 76.1 expected, observed/expected ratio (o/e) 1.05, 90% interval 0.88 to 1.27.
Homologues: Orthologues: chimpanzee NSG2 (100% identical), dog NSG2 (100% identical), guinea pig NSG2 (99% identical), rabbit NSG2 (99% identical), macaque NSG2 (99% identical), pig NSG2 (99% identical), mouse Nsg2 (97% identical), tropical clawed frog nsg2 (80% identical), zebrafish nsg2 (73% identical). Paralogues in human: NSG1 (57% identical), CALY (33% identical).
Diseases named in the same sentence as NSG2 in open-access papers:
NSG2 is named in the same sentence as 9 diseases in open-access papers, as found by Europe PMC text mining. Sharing a sentence is not in itself a finding about the gene and the disease. The quoted sentences say what the papers report.
Anxiety (3 papers, 2022 to 2024). Intense feelings of nervousness, tension, or panic often arise in response to interpersonal stresses. "Surprisingly, we found that NSG2 KO animals displayed normal behavior across multiple motor and anxiety-related domains, but displayed enhanced associative learning and memory across striatal-, amygdala-, and hippocampal-dependent tasks." (PMID 39257983, 2024). "However, taken together, while NSG1 appears critical in motor and anxiety-related pathways, NSG2 and NSG3 may be primarily involved in associative learning and memory via differential AMPAR trafficking." (PMID 39257983, 2024). "Future studies using the conditioned eyeblink task across multiple NSG family member KO mice (e.g., NSG2‐3), could help determine whether the cerebellum may be a locus for anxiety‐related behavioral changes specifically in NSG1 KO mice." (PMID 35577358, 2022). "For instance, NSG2 KO animals performed equivalent to wild-type C57Bl/6n mice on rotarod and Catwalk motor tasks, and did not display alterations in anxiety-like behavior on open field and elevated zero maze tasks." (PMID 39257983, 2024).
breast carcinoma (1 paper, 2024). "In conclusion, this study is the first to identify elevated NSG2 expression in breast cancer, which is linked to poor survival and associated with immune cell abundance and checkpoint expression." (PMID 39493764, 2024). "Kaplan-Meier survival and multivariate analyses identified NSG2 expression in both cancer and stromal cells as an independent prognostic factor for breast cancer survival." (PMID 39493764, 2024). "Our mIHC analysis indicated that NSG2 expression correlates with larger tumor size, distant metastasis, and advanced stage, suggesting its potential as a prognostic marker in breast cancer." (PMID 39493764, 2024). "NSG2 was present in both breast cancer cells and adjacent stromal cells." (PMID 39493764, 2024). "NSG2 may thus be a key prognostic and immunological biomarker for breast cancer." (PMID 39493764, 2024).
glioma (1 paper, 2021). A benign or malignant brain and spinal cord tumor that arises from glial cells (astrocytes, oligodendrocytes, ependymal cells). "A series of genes such as EN1, S100A4, ANXA1, PDPN, IGFBP2 and CHI3L1 were upregulated in radiotherapy treated glioma patients, while other genes such as PRLHR, SFRP2, BRINP1, TRIM67, LHX5, KCNIP2 and NSG2 were downregulated." (PMID 34852024, 2021).
tumor (4 papers, 2015 to 2025). "Pearson χ2 tests indicated that high NSG2 expression in cancer cells was associated with larger tumor size (P = 0.034), distant metastasis (P = 0.036), and advanced clinical stage (P = 0.032)." (PMID 39493764, 2024). "Associations between NSG2 expression, tumor-infiltrating immune cells (TIICs), immune checkpoints, and clinical outcomes were investigated." (PMID 39493764, 2024). "Increased NSG2 expression in cancer cells correlated with greater tumor size, distant metastasis, and more advanced clinical stages." (PMID 39493764, 2024). "Our findings indicate that NSG2 overexpression is associated with increased infiltration of CD4+ and CD8+ T cells near the tumor." (PMID 39493764, 2024). "Although CD8+ T cells are well-documented for their direct tumor-killing abilities, our results suggest that NSG2 may amplify tumor immunogenicity, leading to increased CD4+ and CD8+ T cells populations." (PMID 39493764, 2024).
cancer (2 papers, 2013 to 2024). A tumor composed of atypical neoplastic, often pleomorphic cells that invade other tissues. "Elevated NSG2 levels both in cancer and stroma cells were linked to increased CD4+ T, CD8+ T, and Lamp3+ dendritic cells infiltration in stromal regions (P < 0.05)." (PMID 39493764, 2024). "We determined the optimal cutoff value of NSG2 protein expression in cancer cells using the R package MaxStat." (PMID 39493764, 2024). "Given that NSG2 expression is significantly higher in cancer cells than in stromal cells, further verification of the relationship between NSG2 and CD20+ B cells is warranted." (PMID 39493764, 2024). "Univariate Cox regression of 228 patients showed that high NSG2 protein expression in both cancer and stromal cells, along with T stage, N stage, M stage, and clinical stage, significantly correlated with OS." (PMID 39493764, 2024). "Multivariate analysis confirmed NSG2 expression in cancer and stromal cells as independent prognostic factors for poor outcomes." (PMID 39493764, 2024). "NSG2 expression positively correlated with CD4+ T cells, CD8+ T cells, and Lamp3+ dendritic cells in both cancer and stromal compartment, but negatively correlated with CD20+ B cells in stromal cells." (PMID 39493764, 2024).
psychiatric disorder (2 papers, 2024). A disorder characterized by behavioral and/or psychological abnormalities, often accompanied by physical symptoms. "Given the relevance of disrupted sleep and circadian rhythm endophenotypes to multiple neurological and psychiatric disorders, we assessed the diurnal locomotor activity of NSG2 KO animals using homecage monitoring." (PMID 39257983, 2024).
NSG2 also shares sentences with these, for which no sentence is quoted: candidiasis (1 paper); ductal adenocarcinoma (1); pancreatic cancer (1).